GCN1 (GCN1 activator of EIF2AK4)
Description:
Ribosome collision sensor that plays a key role in the RNF14-RNF25 translation quality control pathway, a pathway that takes place when a ribosome has stalled during translation, and which promotes ubiquitination and degradation of translation factors on stalled ribosomes. Directly binds to the ribosome and acts as a sentinel for colliding ribosomes: activated following ribosome stalling and promotes recruitment of RNF14, which directly ubiquitinates EEF1A1/eEF1A, leading to its degradation. In addition to EEF1A1/eEF1A, the RNF14-RNF25 translation quality control pathway mediates degradation of ETF1/eRF1 and ubiquitination of ribosomal protein. GCN1 also acts as a positive activator of the integrated stress response (ISR) by mediating activation of EIF2AK4/GCN2 in response to amino acid starvation (By similarity). Interaction with EIF2AK4/GCN2 on translating ribosomes stimulates EIF2AK4/GCN2 kinase activity, leading to phosphorylation of eukaryotic translation initiation factor 2 (eIF-2-alpha/EIF2S1) (By similarity). EIF2S1/eIF-2-alpha phosphorylation converts EIF2S1/eIF-2-alpha into a global protein synthesis inhibitor, leading to a global attenuation of cap-dependent translation, and thus to a reduced overall utilization of amino acids, while concomitantly initiating the preferential translation of ISR-specific mRNAs, such as the transcriptional activator ATF4, and hence allowing ATF4-mediated reprogramming of amino acid biosynthetic gene expression to alleviate nutrient depletion (By similarity).
Synonyms: GCN1L1; KIAA0219; GCN1L; PRIC295
Tractability: PROTAC: ubiquitination databases record sites on it; its protein half-life has been measured.
Gene: Protein-coding gene on chromosome 12 (120,127,202 to 120,194,976, reverse strand). Ensembl gene ENSG00000089154.
Subcellular location: Cytoplasm
Subcellular location (Human Protein Atlas): Cytosol
Pathways (Reactome):
Cellular responses to stimuli: Response of EIF2AK4 (GCN2) to amino acid deficiency
Gene Ontology:
Molecular function: cadherin binding; molecular adaptor activity; protein binding; RNA binding; stalled ribosome sensor activity; protein kinase regulator activity; protein serine/threonine kinase activator activity; translation factor activity, RNA binding
Biological process: protein-RNA covalent cross-linking repair; rescue of stalled ribosome; cellular response to amino acid starvation; GCN2-mediated signaling; regulation of translation
Cellular component: cytosol; cytosolic ribosome; membrane; cytoplasm; ribosome
Genetic constraint (gnomAD): Loss-of-function variants: 66 observed, 232.3 expected, observed/expected ratio (o/e) 0.28, 90% interval 0.23 to 0.35. The upper end of that interval is the gene's LOEUF score, 0.35, which puts it in group 1 of 6, group 1 being the genes least tolerant of losing a copy. Missense variants: 2,253 observed, 3,126.1 expected, observed/expected ratio (o/e) 0.72, 90% interval 0.69 to 0.75. Synonymous variants: 1,203 observed, 1,315.5 expected, observed/expected ratio (o/e) 0.91, 90% interval 0.87 to 0.96.
Homologues: Orthologues: chimpanzee GCN1 (99% identical), macaque GCN1 (99% identical), dog GCN1 (97% identical), pig GCN1 (96% identical), guinea pig GCN1 (96% identical), rabbit GCN1 (94% identical), rat Gcn1 (94% identical), mouse Gcn1 (94% identical), tropical clawed frog gcn1 (78% identical), zebrafish gcn1 (71% identical), Drosophila melanogaster l(3)80Fj (43% identical), Caenorhabditis elegans gcn-1 (33% identical). Paralogues in human: ECPAS (12% identical).
Diseases named in the same sentence as GCN1 in open-access papers:
GCN1 is named in the same sentence as 30 diseases in open-access papers, as found by Europe PMC text mining. Sharing a sentence is not in itself a finding about the gene and the disease. The quoted sentences say what the papers report.
hepatocellular carcinoma (2 papers, 2020 to 2022). A malignant tumor that arises from hepatocytes. "On the other hand, GCN1 was recently identified in Mccc2-interacting protein in human hepatocellular carcinoma." (PMID 35328622, 2022).
prostate carcinoma (2 papers, 2022 to 2025). A carcinoma that arises from epithelial cells of the prostate gland. "The N-terminal GTPase (nGTPase) domain is responsible for initiating mitochondrial trafficking and interactions with GCN1 in prostate cancer." (PMID 36050579, 2022). "Many proteins have been determined to interact directly with Miro nGTPases and recently the interaction of Miro2 with GCN1 was shown to be critical in driving prostate cancer progression." (PMID 36050579, 2022). "However, to the best of our knowledge, there are few studies on the relation of GCN1 with cancer except that GCN1 was reported to be overexpressed in prostate cancer." (PMID 41011152, 2025).
cystic fibrosis (1 paper, 2025). Autosomal recessive disorder caused by pathogenic variants in the CFTR gene (cystic fibrosis transmembrane conductance regulator), which encodes a chloride and bicarbonate channel expressed in epithelial cells, and follow the diagnosis criteria. "For example, treatment with readthrough reagents for diseases caused by premature termination codons, as found in Cystic fibrosis and Hurler disease, may induce ribosome collisions at the 3′ poly(A) tail through GCN1 activation." (PMID 38949989, 2025).
developmental delays (1 paper, 2025). "However, in gcn-1(n4857) mutants, rps-10 RNAi did not exacerbate the decrease in oxygen consumption (right plot, P = 0.5, paired Student’s t test), despite causing developmental delays, thereby validating the effective knockdown of rps-10." (PMID 39786340, 2025).
glioblastoma (1 paper, 2021). The most malignant astrocytic tumor (WHO grade IV). "Indeed, the interactome of ERβ5 has been described in glioblastoma cells, and it has been revealed that this receptor can interact with mechanistic target of rapamycin kinase (mTOR) or eIF-2-alpha kinase activator GCN1 to promote cell migration and invasion." (PMID 34068748, 2021).
Hypoglycemia (1 paper, 2022). A decreased concentration of glucose in the blood. "As the histochemical analysis revealed that the number of pancreatic α-cells was not altered in the Gcn1 CKO mice (data not shown), we speculate that GCN1 is involved in the response to hypoglycemia at other points of action." (PMID 35328622, 2022).
Insulin resistance (1 paper, 2022). Increased resistance towards insulin, that is, diminished effectiveness of insulin in reducing blood glucose levels. "The reversibility of this weight loss without apparent decreases of mouse viability suggests the potential value of liver GCN1 as a drug target for obesity or non-alcoholic fatty liver disease leading to insulin resistance, the most prevalent non-communicable disease in the world." (PMID 35328622, 2022).
leukemia (1 paper, 2025). A malignant (clonal) hematologic disorder, involving hematopoietic stem cells and characterized by the presence of primitive or atypical myeloid or lymphoid cells in the bone marrow and the blood. "And, Gcn1-knockdown in MLL1-ELL-transduced bone marrow increased AML latency and survival, suggesting a role for Gcn1 and the ISR in leukemia progression." (PMID 40680841, 2025). "To determine the contribution of Gcn1-degradation to leukemia suppression by Triad1, we co-transduced murine bone marrow cells with an MLL1-ELL expression vector plus vectors to express Triad1-specific shRNAs, Gcn1-specific shRNAs, Triad1-plus Gcn1-specific shRNAs, or scrambled controls." (PMID 40680841, 2025).
lung carcinoma (1 paper, 2025). "Bioinformatic analysis revealed that high expression of MFGM (logrank p = 3.2 × 10−7), ANGL4 (logrank p = 0.0022), and MUC5B (logrank p = 0.00041) was associated with poor overall survival in lung cancer patients, whereas elevated GCN1 levels (logrank p = 0.012) correlated with better survival." (PMID 41011152, 2025).
Ogden syndrome (1 paper, 2025). Ogden syndrome is a rare, genetic progeroid syndrome characterized by a variable phenotype including postnatal growth delay, severe global developmental delay, hypotonia, non-specific dysmorphic facies with aged appearance and cryptorchidism, as well as cardiac arrthymias and skeletal anomalies. "Combined analyses of Ogden syndrome cellular models and HeLa cancer models identified a subset of common N-terminally acetylated proteins, including GCN1, ELOA, PPIA, RPL13A, RPP30, and SAE1." (PMID 40558489, 2025).
tumor (5 papers, 2014 to 2025). "Our findings revealed a total of 35 CpG methylation sites within the GCN1 region, with significantly reduced MFSD12 methylation levels observed in tumor tissue samples compared to normal tissues." (PMID 41194934, 2025). "Within the tumor microenvironment, conditions such as hypoxia and nutrient deprivation can exacerbate cellular stress, leading to dysregulated expression of ANGPTL4 and GCN1." (PMID 41011152, 2025).
cancer (3 papers, 2014 to 2025). A tumor composed of atypical neoplastic, often pleomorphic cells that invade other tissues. "Each gene in this network (gcn-1, abcf-3, sptf-3, pig-1, egl-1, ceh-34 and eya-1) has a human counterpart, some of which are implicated in human diseases, including developmental disorders and cancer." (PMID 25101958, 2014). "Among them, GCN1, a protein involved in regulating protein synthesis and other cellular processes in response to amino acid starvation, stands out as a robust candidate and may serve as a valuable marker for investigating the functions, roles, and mechanisms of NAA10 in various cancer models." (PMID 40558489, 2025).
infection (2 papers, 2019 to 2020). The state of being infected such as from the introduction of a foreign agent such as serum, vaccine, antigenic substance or organism. "Of note, GCN1 acts with GCN20 independently of GCN2 to regulate translation that enhances the response to infection and mitochondrial dysfunction in Arabidopsis." (PMID 32324833, 2020).
neurodegenerative disease (1 paper, 2024). A disorder of the central nervous system characterized by gradual and progressive loss of neural tissue and neurologic function. "GCN1-mediated mechanisms and its interaction with other quality control and stress response signals should be important for proteostasis during aging and neurodegenerative diseases, and may be targeted for drug development." (PMID 38474243, 2024).
GCN1 also shares sentences with these, for which no sentence is quoted: breast carcinoma (2 papers); Alzheimer disease (1); communicable disease (1); endometrial cancer (1); gestational diabetes mellitus (1); Hurler disease (1); hypopharyngeal squamous cell carcinoma (1); non-alcoholic fatty liver disease (1); Obesity (1); osteoarthritis (1); osteosarcoma (1); ovarian carcinoma (1); renal carcinoma (1); respiratory failure (1); vesicoureteral reflux (1); virus infection (1).